VASN (vasorin)
Diseases named in the same sentence as VASN in open-access papers (continued):
Sharing a sentence is not in itself a finding about the gene and the disease.
thyroid cancer (2 papers, 2022 to 2023). "For example, studies have shown that VASN (vasorin) in thyroid cancer promotes the EMT of thyroid cancer cells by triggering the YAP/TAZ pathway." (PMID 36288272, 2022). "Interestingly, the cell surface protein VASN has previously been implicated in the promotion of YAP1/TAZ and EMT activity in thyroid carcinomas." (PMID 37370765, 2023).
bipolar disorder (1 paper, 2015). A disorder of the brain that causes unusual shifts in mood, energy, activity levels and the ability to carry out day-to-day tasks. "We identified three rare deletions in KCNJ6, UNC13C, OTOL1 and 7 rare duplications in CNTNAP2/MIR548F3, CORO7/VASN, DTNB, EMID2, KCNF1, PDPR and SGTA/THOP1 that are present in children with bipolar disorder (and their parents)." (PMID 25887117, 2015).
cardiac interstitial fibrosis (1 paper, 2024). "Masson and Sirius staining showed that cardiac interstitial fibrosis was significantly enhanced in the VASN−/− mice, but no obvious abnormalities were observed in the heart tissues of the VASN+/+ and VASN+/− mice." (PMID 39898320, 2024).
chondrodysplasia (1 paper, 2023). "SLC26A2 is a sulfate transporter and its mutation causes chondrodysplasia, whilst vasorin is a TGF-β-binding protein that inhibits TGF-β signaling, which is known to have crucial roles in joint homeostasis." (PMID 37388246, 2023).
chronic kidney disease (1 paper, 2024). Impairment of the renal function secondary to chronic kidney damage persisting for three or more months. "Indeed, in vivo, aortic VASN expression was reduced in the hyperphosphatemia klotho‐hypomorphic mouse model, a premature age‐ or chronic kidney disease (CKD)‐related vascular calcification model." (PMID 38975316, 2024).
dilated cardiomyopathy (1 paper, 2022). Cardiomyopathy which is characterized by dilation and contractile dysfunction of the left and right ventricles. "Our RNA sequencing results revealed that VASN deficiency induced obvious changes in multiple signalling pathways, including ECM‐receptor interactions, the PPAR signalling pathway, cardiac muscle contraction and dilated cardiomyopathy." (PMID 34854218, 2022).
glaucoma (1 paper, 2022). Increased pressure in the eyeball due to obstruction of the outflow of aqueous humor. "ELISA assay revealed a significant but marginal decrease in vasorin levels in the AH of primary open‐angle glaucoma patients compared to non‐glaucoma cataract patients." (PMID 35170203, 2022). "Taken together, this study sheds light on novel findings regarding the role of vasorin in TM cells and the propensity for decreased vasorin levels in the AH of glaucoma patients." (PMID 35170203, 2022). "Since elevated levels of TGF‐β, EndMT (endothelial‐to‐mesenchymal transition) and fibrogenic activities are presumed to play a part in ocular hypertension and glaucoma, we determined the effects of vasorin on TGF‐β2 mediated activation of SMAD2/3, and expression of α‐SMA and fibronectin in TM cells." (PMID 35170203, 2022). "Collectively, these experimental and clinical findings indicate not only a role for vasorin in regulating TM cell physiology and survival, but also suggest that vasorin may possess potential as a therapeutic agent for lowering IOP in glaucoma patients." (PMID 35170203, 2022). "To identify secretory proteins including vasorin that play a potential role in regulating TM cell biology and AH drainage through the trabecular pathway, we performed mass spectrometry (LC‐MS/MS) based analysis of AH (10 μl) derived from several non‐glaucoma (cataract) patient donors." (PMID 35170203, 2022). "Vasorin levels in the AH of POAG patients (mean ± SEM; 621.89 ± 6.91 pg/ml) were marginally (by 4.4%) but significantly (p > 0.05) lower than those in non‐glaucoma patients (649." (PMID 35170203, 2022). "Since vasorin is known to be involved in several diseases, we determined the levels of vasorin in AH derived from twenty‐one POAG patients and twenty age‐ and gender‐matched non‐glaucoma (cataract) patients by ELISA." (PMID 35170203, 2022). "Additionally, vasorin expression is known to be decreased with ageing and by angiotensin II, leading to augmentation of TGF‐β induced fibrotic activity in the vascular smooth muscle cells of arterial wall, and the role of angiotensin II in ocular hypertension and glaucoma is well‐recognized." (PMID 35170203, 2022). "Vasorin levels in aqueous humour of POAG and non‐glaucoma patients were also not significantly correlated with patient age." (PMID 35170203, 2022).
Hepatitis (1 paper, 2015). Inflammation of the liver. "The results confirmed that VASN mRNA was more highly expressed in HCC tissues than those in hepatocirrhosis, hepatitis or pericarcinoma tissues, providing additional evidence for vasorin as a potential HCC marker." (PMID 25826090, 2015). "VASN was verified to be highly expressed in sera of 100 cases of HCC patients compared with 97 cases of normal persons and 129 cases of hepatitis patients." (PMID 25826090, 2015).
hyperandrogenism (1 paper, 2025). Excessive secretion of androgens from the adrenal glands or gonads. "Given that hyperandrogenism is a hallmark of PCOS, future studies should explore the relationship between vasorin and androgen levels to assess its role in the hormonal dysregulation seen in PCOS." (PMID 40137147, 2025).
hyperprolactinemia (1 paper, 2025). Abnormally high level of prolactin in the blood. "Given that hyperprolactinemia is observed in some PCOS phenotypes, future studies should explore whether prolactin directly influences vasorin expression, potentially providing insights into PCOS heterogeneity." (PMID 40137147, 2025).
Insulin resistance (1 paper, 2025). Increased resistance towards insulin, that is, diminished effectiveness of insulin in reducing blood glucose levels. "Although vasorin is involved in inflammatory and oxidative-stress pathways, its association with insulin resistance and lipid metabolism remains unclear based on this study." (PMID 40137147, 2025).
iron deficiency (1 paper, 2025). "Concurrently, a ferroptosis cluster (comprising of Cp, FTL1, and VASN) highlights that iron deficiency triggers the secretion of molecules involved in iron scavenging and oxidative stress regulation." (PMID 40590312, 2025).
myocardial infarction (1 paper, 2024). Gross necrosis of the myocardium, as a result of interruption of the blood supply to the area, as in coronary thrombosis. "After myocardial infarction, local tissue ischemia and hypoxia can trigger a series of pathophysiological changes, and VASN is known to be involved in regulating the balance between apoptosis and regeneration of the myocardial cells." (PMID 39898320, 2024).
Nephropathy (1 paper, 2018). A nonspecific term referring to disease or damage of the kidneys. "No human disease has been associated with variants of this gene so far, but VASN seems to be a potential biomarker for nephropathies and tumorigenesis." (PMID 30564578, 2018). "Interestingly, VASN was upregulated in diabetic patients with nephropathy in contrast to diabetic patients without nephropathy." (PMID 30564578, 2018). "Considering data on the expression of Vasorin in humans or in animal models, one may not be surprised to encounter an altered expression of this protein in human diseases such as nephropathies or cancers." (PMID 30564578, 2018).
ocular hypertension (1 paper, 2022). Abnormally high intraocular pressure. "However, we have no knowledge regarding the role and significance of vasorin in AH, and its possible involvement either in the physiology of the TM or in the aetiology of ocular hypertension." (PMID 35170203, 2022).
polycystic ovary syndrome (1 paper, 2025). A disorder that manifests as multiple cysts on the ovaries. "In this study, we investigated the potential role of vasorin as a novel biomarker in polycystic ovary syndrome (PCOS) and found that serum vasorin levels were significantly lower in PCOS patients compared to healthy controls." (PMID 40137147, 2025).
pregnancy disorder (1 paper, 2025). A disorder that is related to pregnancy. "Vasorin (VASN), a known regulator of the TGF-β signaling pathway, is a promising candidate for investigation in pregnancy disorder." (PMID 41311505, 2025).
prostate carcinoma (1 paper, 2022). A carcinoma that arises from epithelial cells of the prostate gland. "VASN has been reported to promote proliferative ability in prostate cancer." (PMID 35233325, 2022).
prostate tumor (1 paper, 2022). "However, overexpression of VASN in prostate tumor tissue and in serum from PCa patients and the subsequent promotion of cell proliferation and PCa progression have already been reported, in agreement with other types of cancer." (PMID 35454907, 2022).
rectal cancer (1 paper, 2024). A primary or metastatic malignant neoplasm that affects the rectum. "In our study, we found that rectal cancer patients with pulmonary metastasis had higher expression of VASN, which is typically associated with advanced TNM stage." (PMID 39107788, 2024). "This recommendation underscores the importance of targeting VASN and its associated pathways as a promising therapeutic approach for managing rectal cancer." (PMID 39107788, 2024). "This study aims to investigate the impact of VASN in rectal cancer with pulmonary metastasis and understand the underlying molecular mechanisms to guide adjuvant chemotherapy selection." (PMID 39107788, 2024). "Both experimental and clinical data support that rectal cancer patients with VASN overexpression detected in biopsies have a higher risk of pulmonary metastasis and adjuvant chemotherapy resistance." (PMID 39107788, 2024). "In addition, high VASN expression was associated with a lower rectal cancer site, a higher incidence of recurrence and metastasis, and worse overall survival (30.8% five-year survival rate)." (PMID 39107788, 2024). "Further analysis of VASN expression in patients with rectal cancer at different stages revealed that VASN expression increased as the disease progressed." (PMID 39107788, 2024). "Moreover, the Cox analysis and OS analysis indicated that VASN was an independent prognostic factor for OS (HR = 7.4, P value < 0.001) and a predictor of adjuvant therapy efficacy in rectal cancer." (PMID 39107788, 2024). "Although rectal cancer patients without high-risk factors currently do not require adjuvant therapy, our findings suggest that VASN-negative patients should receive adjuvant chemotherapy, as this approach may improve survival." (PMID 39107788, 2024). "Our study revealed a significant correlation between VASN expression and pulmonary metastasis events and a poor prognosis in CRC patients, particularly in mid-low rectal cancer cases." (PMID 39107788, 2024). "In conclusion, our research confirmed for the first time that VASN acts as an oncogene, promoting pulmonary metastasis through the activation of the MAPK and NOTCH pathways in rectal cancer." (PMID 39107788, 2024).
tumor (20 papers, 2015 to 2026). "Consistent findings were observed in the analysis of the Memorial Sloan Kettering Cancer Center (MSKCC) dataset, which showed that high VASN expression was associated with postoperative recurrence and lower tumor location." (PMID 39107788, 2024). "The underlying mechanism by which VASN influences tumor progression was also investigated." (PMID 39107788, 2024). "VASN, crucial in tumor growth and angiogenesis, displays upregulated expression in CRC compared to normal tissues." (PMID 39936032, 2025). "An increasing number of studies have shown that VASN is highly expressed in different tumor cells to regulate tumor progression." (PMID 40430053, 2025). "The results showed that VASN overexpression significantly increased the growth rate and tumor size, while VASN knockdown suppressed growth." (PMID 39107788, 2024). "Another transmembrane glycoprotein expressed in EVs from HCC cells, Vasorin (VASN), is reported with pro-angiogenic functions and can promote tumor cell proliferation and migration through activation of the STAT3 signaling pathway." (PMID 39227992, 2024). "Vasorin is a type I transmembrane protein that plays important role in tumor development and vasculogenesis." (PMID 35155236, 2022). "Serum Vasorin levels were higher among patients with advanced disease and related to the clinical stage of the locally advanced tumor." (PMID 35233325, 2022). "Vasorin (VASN) is a transmembrane glycoprotein that plays an important role in vasculogenesis and tumor development." (PMID 27713136, 2017). "Despite the importance of TGF-β in tumor progression, the status and function of VASN in tumors are seldom reported." (PMID 25826090, 2015). "VASN has been reported to be critical in tumor development and angiogenesis." (PMID 39936032, 2025). "VASN is upregulated under hypoxic or tumorigenic conditions to regulate tumor progression." (PMID 40430053, 2025). "Moreover, VASN expression levels in tumor samples were examined and analyzed for their correlations with pulmonary metastasis status, tumor stage, adjuvant chemotherapy benefit, and survival outcome." (PMID 39107788, 2024). "Vasorin regulates vascular repair in response to injury, inhibits signaling of transforming growth factor-beta, and may play a role in tumor formation." (PMID 35395780, 2022). "In addition, vasorin levels further rose as the disease advanced to higher TNM (tumor (T), nodes (N), and metastases (M)) stages." (PMID 35233325, 2022). "Results from this study indicated that vasorin could be one of the key mediators of communication between tumor cells and endothelial cells." (PMID 35155236, 2022). "In contrast to tubular and alveolar structures, these morphological variants demonstrate high expression of the VASN gene which is known to be enriched in the trailblazer cells and begin to express the MMP14 gene (MT1-MMP) that is essential for tumor cell invasion." (PMID 28977854, 2017). "Furthermore, we identified VASN as a putative regulator of malignant stem phenotypes that may influence tumor microenvironment remodeling." (PMID 42212140, 2026). "The results showed that the knockdown of VASN in U118 cells led to increased activation of Jurkat cells, whereas the overexpression of sVASN in U87 cells resulted in attenuated activation of Jurkat cells, indicating the immunosuppressive effects of sVASN within the tumor microenvironment." (PMID 40430053, 2025). "A correlation between VASN and p-ERK protein expression in tumor tissues was also observed, further confirming the activation of the MAPK pathway by VASN in tumor tissues." (PMID 39107788, 2024). "Univariate independent prognostic analysis showed that age (p < 0.001), tumor grade (p < 0.001), PCDH18 (p < 0.05), PPL (p < 0.01), DEPP1 (p < 0.01), VASN (p < 0.001), KCNE4 (p < 0.001), MYBPH (p < 0.001), C5AR2 (p < 0.01), and MARCH4 (p < 0.01) gene expression levels were significantly different." (PMID 39281062, 2022).
tumor (continued). "GRN, CD5L, ENO1, CHL1, CRISP3, VASN, and TNIK promote the invasive ability of tumor cells." (PMID 32953262, 2020).
cancer (11 papers, 2012 to 2025). A tumor composed of atypical neoplastic, often pleomorphic cells that invade other tissues. "In terms of the mean fluorescence density, the protein levels of VASN in the sVASN treatment group (red) were significantly greater than those in the other groups, indicating the persistent effect of sVASN on cancer proliferation." (PMID 40430053, 2025). "VASN is known for its involvement in TGF-β regulation, but it has also been linked to cancer lately." (PMID 41311505, 2025). "Cancer cells with gradient descent (U118) or elevation (U87) levels of VASN were co-cultured with activated Jurkat cells to detect the inhibition of activated Jurkat cells." (PMID 40430053, 2025). "The results revealed that the overexpression of sVASN in cancer cells significantly increased VASN protein levels in Jurkat cells." (PMID 40430053, 2025). "Vasorin (VASN) is a type I membrane protein, and its oncogenic function has been reported in various cancers." (PMID 39107788, 2024). "Vasorin (Vasn) is a pleiotropic molecule involved in various physiological and pathological conditions, including cancer." (PMID 39157725, 2024). "VASN has been identified as an oncogene in various cancers, such as glioma, thyroid cancer, and prostate cancer." (PMID 39107788, 2024). "Following this idea but in another domain, Vasorin was also identified in a few studies looking for cancer biomarkers." (PMID 30564578, 2018). "The expression of VASN mRNA and protein in various human cancer and normal cell lines was measured by real-time PCR and Western blot respectively." (PMID 25826090, 2015). "VASN has also been found as a possible biomarker linked to epithelial-mesenchymal transition (EMT) in thyroid and colorectal malignancies, which is a vital stage in cancer metastasis." (PMID 41311505, 2025). "VASN has been identified in several high-throughput screens as a potential cancer biomarker." (PMID 35233325, 2022). "This indicates that VASN could act as a mediator for cancer cells toward their environment, promoting endothelial cells invasion and consecutively tumor development and metastasis." (PMID 30564578, 2018). "Since VASN is expressed on the cell surface, these results suggested that VASN could be an effective biological target of cancer treatment." (PMID 25826090, 2015). "The relationship between VASN and CD71 is more likely to involve a ligand–receptor interaction, such as that between PD-L1 and PD-1 in cancer cells and immune cells." (PMID 40430053, 2025). "We employed a co-culture system to examine the expression levels of VASN and CD71 in both cancer cells and T cells." (PMID 40430053, 2025). "VASN, vasorin, is a transforming growth factor beta (TGF-β) trap, its biology is regulated by ADAM17, and it appears to play a role in epithelial to mesenchymal transition in other cancer types." (PMID 23251904, 2012).
cardiovascular diseases (2 papers, 2024). "Understanding these molecular physical and functional interactions may pave the way for establishing VASN‐based therapeutic strategies to counteract adverse age‐associated cardiovascular remodeling, eventually reducing the risk of cardiovascular diseases." (PMID 38975316, 2024). "The VASN gene is important for the occurrence and development of cardiovascular diseases." (PMID 39898320, 2024).
VASN also shares sentences with these, for which no sentence is quoted: adenocarcinoma (1 paper); atrioventricular block (1); B type hepatitis (1); gastrointestinal tumors (1); heart disease (1); heart failure (1); infection (1); leukemia (1); lung carcinoma (1); Myocardial fibrosis (1); osteoarthritis (1); preeclampsia (1); steatosis (1); Urea (1).